LHFPL4 (LHFPL tetraspan subfamily member 4)
Description:
Plays a role in the regulation of inhibitory synapse formation and function by being involved in maintening gamma-aminobutyric acid receptors (GABAARs) clustering and their associated scaffold proteins at inhibitory synaptic sites. Acts in concert with NLGN2 to recruit or stabilize GABAARs.
Synonyms: GARLH4
Tractability: Antibody: UniProt places it where antibodies can reach, with medium confidence; UniProt predicts a signal peptide or a membrane-spanning region; its Gene Ontology location is reachable by antibodies, with medium confidence.
Gene: Protein-coding gene on chromosome 3 (9,498,361 to 9,553,823, reverse strand). Ensembl gene ENSG00000156959.
Subcellular location: Cell projection, dendrite; Postsynaptic cell membrane
Subcellular location (Human Protein Atlas): Golgi apparatus; Nucleoplasm
Gene Ontology:
Molecular function: protein binding; GABA receptor binding
Biological process: gamma-aminobutyric acid receptor clustering; regulation of inhibitory synapse assembly; sensory perception of sound; neurotransmitter receptor localization to postsynaptic specialization membrane
Cellular component: inhibitory synapse; plasma membrane; postsynaptic membrane; dendrite; GABA-ergic synapse; postsynaptic specialization
Genetic constraint (gnomAD): Loss-of-function variants: 6 observed, 19.97 expected, observed/expected ratio (o/e) 0.3, 90% interval 0.16 to 0.59. The upper end of that interval is the gene's LOEUF score, 0.59, which puts it in group 2 of 6, group 1 being the genes least tolerant of losing a copy. Missense variants: 208 observed, 342.41 expected, observed/expected ratio (o/e) 0.61, 90% interval 0.54 to 0.68. Synonymous variants: 129 observed, 146.8 expected, observed/expected ratio (o/e) 0.88, 90% interval 0.76 to 1.02.
Homologues: Orthologues: chimpanzee LHFPL4 (99% identical), macaque LHFPL4 (99% identical), pig LHFPL4 (99% identical), dog LHFPL4 (98% identical), mouse Lhfpl4 (98% identical), rat Lhfpl4 (98% identical), rabbit LHFPL4 (98% identical), guinea pig LHFPL4 (97% identical), tropical clawed frog lhfpl4 (83% identical), zebrafish lhfpl4a (71% identical), Drosophila melanogaster Tmhs (36% identical). Paralogues in human: LHFPL3 (69% identical), LHFPL5 (54% identical), LHFPL2 (21% identical), LHFPL6 (21% identical), LHFPL1 (20% identical), LHFPL7 (18% identical).
Diseases named in the same sentence as LHFPL4 in open-access papers:
LHFPL4 is named in the same sentence as 4 diseases in open-access papers, as found by Europe PMC text mining. Sharing a sentence is not in itself a finding about the gene and the disease. The quoted sentences say what the papers report.
cervical cancer (1 paper, 2018). A primary or metastatic malignant neoplasm involving the cervix. "The LHFPL4 gene at 3p25.3 was identified as a novel methylation target specific for cervical cancer." (PMID 29914565, 2018).
lipoma (1 paper, 2021). A benign, usually painless, well-circumscribed lipomatous tumor composed of adipose tissue. "The LHFPL4 gene is a member of the lipoma HMGIC fusion partner (LHFP) gene family, which is a subset of the superfamily of tetraspan transmembrane protein-encoding genes." (PMID 35052436, 2021).
LHFPL4 also shares sentences with these, for which no sentence is quoted: kidney cancer (1 paper); ovarian carcinoma (1).